ARAFP2 (ARAF pseudogene 2)
Synonyms: PKS1; formerly ARAF2; ARAFPS; ARAF2P
Gene: Processed pseudogene on chromosome 7 (63,404,842 to 63,405,400, reverse strand). Ensembl gene ENSG00000224368.
Diseases named in the same sentence as ARAFP2 in open-access papers:
ARAFP2 is named in the same sentence as 4 diseases in open-access papers, as found by Europe PMC text mining. Sharing a sentence is not in itself a finding about the gene and the disease.
ARAFP2 shares sentences with these, for which no sentence is quoted: infection (11 papers); co-infection (1); skin infection (1); tumours (1).